IL6 (interleukin 6)
Diseases named in the same sentence as IL6 in open-access papers (continued):
Sharing a sentence is not in itself a finding about the gene and the disease.
Anorexia (continued). "In addition, IL-6 seems to contribute to loss of appetite in anorexia." (PMID 34771524, 2021). "According to these models, anorexia was associated with GDF15 and IL-6 concentrations above at least 131 pg/mL and 450 pg/mL, respectively." (PMID 40124481, 2025). "Inflammatory cytokines IL-18 and IL-6 can further activate the NF-κB signaling pathway, regulating POMC activity to cause anorexia." (PMID 39691381, 2024). "Mice in this model show a persistent increase in blood IL-6 levels, followed by robust cachectic phenotypes, including anorexia and dramatic bodyweight loss." (PMID 38824130, 2024). "At the cellular level, cytokines such as IL-6 interfere with the satiety center, leading to anorexia, delayed gastric emptying, and skeletal muscle protein catabolism." (PMID 36937339, 2023). "TNF and IL-6, both known contributors to oral premalignant conditions and oral malignancies, have been observed to induce anorexia in affected individuals." (PMID 38169924, 2023). "Proinflammatory cytokines, such as IL-6, induce anorexia and increase the incidence of chronic fatigue and muscle protein degradation." (PMID 37763079, 2023). "For IL-6, and TNFα, the literature supports relationships of these markers with anorexia and skeletal muscle breakdown." (PMID 37906352, 2023). "Within these pathways, many cell cytokines, including those associated with inflammation, such as IL-1, IL-6, TNF-10, IL-22, and TNF-alpha, contribute to the anorexia of cancer patients." (PMID 34724970, 2021). "Similar increases of IL6 and IL1β gene expressions were found in the hippocampus of young female rats in the dehydration-induced anorexia model." (PMID 33580474, 2021). "Among TNF-α, TGF-β, and IL-6, the post-/pretreatment ratio of TGF-β after 12 weeks was associated with TKI-induced anorexia, and the ratios after 10 and 12 weeks were associated with fatigue." (PMID 33050250, 2020). "Gaigé and co-workers indicated that T-2-induced anorexia correlated with IL-1β, IL-6, and TNF-α mRNA upregulation in the spleen and liver." (PMID 29710820, 2018). "Through increasing gene expression of anorexia-inducing proinflammatory cytokines such as interleukin-1β (IL-1β), interleukin-6 (IL-6) and tumor necrosis factor-α (TNF-α), trichothecenes exacerbate the condition of anorexia." (PMID 29535978, 2018). "Siltuximab has been reported to reduce cancer-related anorexia and cachexia and neutralize the effect of IL-6 in different types of human malignancies." (PMID 28927416, 2017). "This anorexigenic effect of TNFα and IL-6 showed to coincidence with increased hypothalamic serotonergic activity, providing further evidence for a role for serotonin in inflammation-induced anorexia." (PMID 27207102, 2016). "Third, while both peripheral and central injection of IL-1β into rodents elicits anorexia in rodents, only central injection of IL-6 suppresses food intake." (PMID 26492270, 2015). "Cancer-induced anorexia and cachexia involve proinflammatory cytokines such as IL-6, MCP-1, and TNF-α." (PMID 24963216, 2014). "IL-6 is known to stimulate protein catabolism in order to maintain glucose levels via gluconeogenesis, whereas anorexia, is largely driven by IL-1β and is known to mobilize fat stores in lieu of protein stores." (PMID 19216742, 2009). "Studies using experimental models show clearly that the proinflammatory cytokines, including IL-1, IL-6, and TNFα are intermediaries of anorexia and that fatigue, poor functionality, and a poor QoL are also factors related to these inflammatory markers, predicting overall survival and prognosis." (PMID 38744744, 2024). "In order to investigate the potential roles of pro-inflammatory cytokines IL-18 and IL-6 in anorexia induction, mice were exposed with a common anorexigenic dose of 2.5 mg/kg BW DON, 3-ADON, 15-ADON, NIV and FX by two methods (IP vs. oral) using a previously established mouse anorexia model." (PMID 39691381, 2024).
Anorexia (continued). "In addition, the temporal relationship of DON and its congeners-induced IL-18, as well as IL-6 expression, was found to be consistent with their resulting anorexia." (PMID 39691381, 2024). "The IL6/STAT3 signaling pathway has been implicated in cancer cachexia, a multifactorial condition that presents with skeletal muscle wasting, adipose tissue atrophy, and anorexia." (PMID 30072615, 2018). "Elevated tissue IL-1β might be more important to DON-induced anorexia than the observed IL-6 increase for several reasons." (PMID 26492270, 2015). "IL-1β and IL-6 are regarded as the key pro-inflammation cytokines triggering the acute phase reaction in the liver and modifying the brain-controlled functions such as fever and anorexia." (PMID 24345215, 2013). "It has been reported that NF-κB and C/EBP DNA binding activity are responsible for TNF-α induced IL-6 expression via PPAR-γ, and inhibition of PPAR-γ might be the reason for decreased levels of TNF-α induced IL-6 expression which are mediators of anorexia." (PMID 24381940, 2013). "Moreover, we speculate that IL-18 and IL-6 in the toxin-induced anorexia response directly acts on the hypothalamus to regulate the appetite center." (PMID 39691381, 2024). "Thus, it seems that IL‐6 can play a crucial role in exercise‐induced anorexia." (PMID 39722170, 2024). "Indeed, cytokines (e.g., TNF-a, IL-1a, IL-1b and IL-6) can directly cause neuronal apoptosis and produce a stereotyped cluster of nonspecific signs such as impaired concentration, anorexia, fatigue, diminished motivation, depression, and anorexia." (PMID 35964069, 2022). "Furthermore, intracerebroventricular co-infusion of IL-6 and IL-1β in doses that do not affect food intake when administered individually causes anorexia." (PMID 33255553, 2020). "Therefore, it might be speculated that anorexia induction by trichothecenes could be mediated by the pro-inflammatory cytokines IL-1β, IL-6, and TNF-α as part of sickness behavior." (PMID 29710820, 2018). "Furthermore, inflammatory mediators, such as interferon-gamma (IFN-γ), interleukin-6 (IL-6) and tumor necrosis factor-alpha (TNF-α) may contribute to anorexia, adipose tissue loss and muscle atrophy." (PMID 22761662, 2012). "Although the catabolism is mainly mediated by the effects of certain cytokines, such as tumor necrosis factor-α (TNF-α), interleukin-1β (IL-1β), and interleukin-6 (IL-6), the mechanisms associated with cancer related anorexia are still not elucidated completely." (PMID 20920199, 2010). "Cytokines such as IL-1, IL-6 and TNF-α play central roles in orexia regulation, often promoting anorexia by activating mechanisms that inhibit appetite." (PMID 40046187, 2024). "Tumour-driven cytokines, such as growth differentiation factor 11, IL-1β, IL-6 leukaemiaia inhibitory factor, TNF-α, and TGFβ1 promote cancer cachexia with anorexia in the brain, proteolysis in the skeletal muscles, and browning in the WAT." (PMID 35406121, 2022). "It is worth noting that there seems to be a consensus that the activation of IL-6 expression follows the up-regulated expression of LIF, thereby promoting the occurrence of anorexia and cachexia syndrome in tumor patients." (PMID 35740622, 2022). "Increases in IL-1β and TNF contribute to anorexia, and TNF and IL-6 promote lipolysis and inhibit lipogenesis in WAT leading to weight loss." (PMID 32934774, 2020). "Elevations of IL-1β, IL-6, and TNF-α were observed in DON-administered mice that were correlated to DON-induced anorexia." (PMID 29710820, 2018). "Cachexia often appears with anorexia as a result of imbalances between pro-inflammatory (e.g., TNF-α, IL-1, IL-6, interferon-gamma [IFN-γ]) and anti-inflammatory cytokines (e.g., interleukin-4 [IL-4], interleukin-12 [IL-12], interleukin-15 [IL-15])." (PMID 28177923, 2017). "Both IL-6 and GDF15 have been functionally involved in cancer anorexia-cachexia." (PMID 40124481, 2025).
Anorexia (continued). "Based on this, we hypothesized that the expression of inflammatory cytokines (IL-18, IL-6) induced by DON and its congeners may lead to anorexia by altering the composition of the intestinal flora and consequently." (PMID 39691381, 2024). "Using IFN-I receptor 1 (IFNAR1)-deficient mice, the results of the authors present suggest that IFN-I are involved in the induction of sickness behavior, including anorexia, whereas IL-6 participates in sickness behavior but not in anorexia." (PMID 28855891, 2017). "Addition of IL-6 is sufficient to reconstitute full expression of some measures of altered CNS function such as burrowing, but not anorexia." (PMID 25900439, 2015). "This is supported by experimental models whereby pro-inflammatory cytokines, including interleukin-1 (IL-1), IL-6 and tumour necrosis factor-ά (TNF), have been reported as mediators of both anorexia and skeletal muscle proteolysis, the key components of weight loss in patients with cancer." (PMID 22870258, 2012). "Additionally, a study using the dehydration-induced anorexia model, elevated levels of the inflammatory markers were reported (TNF-α, IL-6, and IL-1β), suggesting the possibility of an environment conducive to neuroinflammation with suggested correlation with neurodegeneration." (PMID 40269196, 2025). "In this study, we focused on two common pro-inflammatory cytokines (IL-18, IL-6), and investigated the anorexigenic potency of DON and its congeners and the release of IL-18 and IL-6 in plasma under different methods (oral vs. IP) based on anorexia models in mice." (PMID 39691381, 2024). "In addition, inflammatory markers, such as IL1, IL6 and TNF-α which are known to induce anorexia or may have stronger impact on appetite and food intake compared with CRP, were not measured in the present study." (PMID 32618518, 2020). "Accumulating evidence indicates that systemic inflammation and pro-inflammatory cytokines, including TNF-β, IL-6 and IL-1β, are major factors in promoting muscle atrophy through UPS activation, muscle differentiation and myogenesis inhibition, and improvement of anorexia during cancer cachexia." (PMID 29731967, 2018). "Importantly, we demonstrated that these alterations in gut microbiota and gut barrier function are related to the increased level of IL-6 rather than to the anorexia." (PMID 29719601, 2018). "However, whether IL-18 and IL-6 are involved in the anorexia induced by DON and its congeners is not clear." (PMID 39691381, 2024). "Reconstitution of circulating IL-6 revealed that the role of IFNAR in burrowing activity is mediated via IL-6, while IFN-I and IL-6 have additive effects on hypoactivity, but the role of IFN-I in anorexia is independent of IL-6." (PMID 25900439, 2015).
Fever (103 papers, 2008 to 2026). Body temperature elevated above the normal range. "Other pro-inflammatory cytokines, such as TNF-α, IL-1β and IL-6, are thought to be associated with fever and multi-organ dysfunction in HLH." (PMID 40842582, 2025). "Fever was associated with elevated plasma levels of interleukin-6 (IL-6) (224 pg/mL) and C-reactive protein (CRP) (117.6 mg/L)." (PMID 40705122, 2025). "This instant acute-phase reaction resulting in pyrexia, exhaustion or chills is thought to be caused by the release of pro-inflammatory cytokines, such as IL-6 and TNF-a." (PMID 34018012, 2022). "Fever is known to be caused by several endogenous pyrogens such as interleukin-1β (IL-1β) and IL-6, interferon-α (IFN-α), tumor necrosis factor-α (TNF-α), macrophage protein-1, and prostaglandins such as PGE2 and PGI2." (PMID 33747115, 2021). "It has been reported that injection of recombinant IL-6 in rats and rabbits caused pyrexia, and that IL-6 was significantly higher in pheochromocytoma patients with high body temperature than in pheochromocytoma patients with normal body temperature." (PMID 33715142, 2021). "Pyrexia in these patients is caused by IL-6 that crosses the blood–brain barrier and initiates synthesis of prostaglandin E2 (PGE2) in the hypothalamus, which results in changing the setpoint of body temperature." (PMID 33715142, 2021). "Antipyretic agents workby lowering the hypothalamic setpoint, which is increased during pyrexia.Endogenous pyrogens, such as interleukin-1 and interleukin-6, cause febrileresponse by stimulating cerebral prostaglandin-E synthesis." (PMID 18509484, 2008). "The level of IL-6 is directly associated with both fever and the strength of the acute phase response, so excluding patients with fever or infectious diseases may explain the protective effect of IL-6 on specific ethnic populations." (PMID 40305179, 2025). "Fever is known to be the most frequent symptom of cytokine storms, mainly associated with the over-activation of neutrophils, monocytes, macrophages, T cells and massive release of cytokines (such as IL-6, IL-2, IFN-γ, TNF-α)." (PMID 39127636, 2024). "These activated cells released proimflammatory cytokines such as TNF-α, IL-1 and IL-6, which could cause fever, hyperferritinemia and other symptoms." (PMID 28196537, 2017). "During heat stress, body temperature increases and homeostasis of the intestinal flora becomes disrupted, which may cause inflammatory factors such as TNF-α, IL-6, IL-8, among others, to be released into the circulation, which can lead to fever." (PMID 27857180, 2016). "Plasma levels of inflammatory cytokines (PGE2, IL-1β, and IL-6) were significantly elevated (p < 0.05) in V. harveyi-challenged seahorses under thermal gradient conditions (fever group) compared to those maintained at constant temperature (no fever group)." (PMID 40508975, 2025). "Accordingly, several other studies reported the anti-inflammatory effect of borneol, by showing its capacity to inhibit pro-inflammatory mediators such as NO, TNF-α and IL-6 in LPS-stimulated macrophages and by decreasing fever in a model of endotoxic fever." (PMID 36671380, 2023). "The selected genes, il1b, tnfa, and il6, showed more robust local induction of gene expression under dynamic fever conditions (TD group), where fish had been allowed to swim freely through the established 10°C temperature gradient within the ATPT." (PMID 36917159, 2023). "TPDM6315 reduced the nitric oxide production and expressions of the COX2, PGE2 TNF-α, and IL-6 genes, indicating a possible anti-inflammatory effect of this recipe, which has been traditionally used to treat fever." (PMID 37367060, 2023). "Fever is a common brain-mediated antitraumatic, infective, or non-infective inflammatory response mediated by endogenous pyrogens such as IL-6, TNF-α, PGE2, corticotropin-releasing factor, and endothelin-1." (PMID 35736412, 2022).
Fever (continued). "The incidence of pyrexia involves many mediators, such as interleukins IL-6, IL-1β, IL-8, and TNF-α, as recorded in previous studies." (PMID 34641376, 2021). "Fever symptoms and elevated IL-6 levels (> 2.9 pg/ml) on admission were significantly associated with lower likelihood of the discharge." (PMID 33628107, 2021). "Fever symptoms (HR=0.57; 95% CI 0.36-0.90) and elevated IL-6 levels (> 2.9 pg/ml) on admission (HR=0.50; 95% CI 0.30-0.86) were unfavorable factors for discharge (all HRs <1 and all P-values <0.05)." (PMID 33628107, 2021). "Fever (HR=0.57; 95% CI 0.36-0.90) and IL-6 levels greater than 2.9 pg/ml (HR=0.50; 95% CI 0.30-0.86) were unfavorable factors for discharge." (PMID 33628107, 2021). "Fever is pivotal in the response to infection and the pyrogenic cytokine interleukin 6 (IL-6) has multilevel effects on the immune system." (PMID 33066823, 2020). "The almost identical increases in IL-6 levels compared to the corresponding controls underline the transferability of the whole blood assay to in vivo inhalation exposure and could enable the usage of whole blood assays as a prognostic tool to predict the occurrence of metal fume fever." (PMID 30718726, 2019). "Of note, high levels of L-valine were observed in pyrexia rats with accumulated expression of IL-6 and TNF-α." (PMID 31143120, 2019). "The occurrence of pyrexia involves numerous nerval routes and factors, such as interleukin 6 (IL-6) and tumor necrosis factor alpha (TNF-α)." (PMID 31143120, 2019). "In all cases, patients with IL-6 ectopic secretion presented with pyrexia resistant to any treatment, which resolved after surgical debulking of the tumor." (PMID 31137729, 2019). "One of the patients with a metastatic PGL presented with refractory pyrexia due to ectopic secretion of IL-6, confirmed by elevated IL-6 levels in the serum and histological confirmation of IL-6 protein expression in the tissue." (PMID 31137729, 2019). "The pro-inflammatory cytokine interleukin-1β serves as the main endogenous pyrectic substance in initiating fever and works synergistically with interleukin-6 and TNF-α." (PMID 31174289, 2019). "Accumulating evidences, obtained from animal model studies, suggested that the levels of TNF-α and IL-6 were increased following yeast-induced fever." (PMID 31143120, 2019). "IL-6 is regarded as an endogenous mediator of LPS-induced fever and IL-1β can initiate and enhance the inflammatory response." (PMID 31842849, 2019). "The two patients 10 and 14 who experienced myalgia and pyrexia accompanied by increased CRP also showed elevated IL-6 levels, with the highest levels 67.23 pg/mL and 87.96 pg/mL, respectively." (PMID 29268708, 2017). "Only calves inoculated with vital Cp developed fever (peak at 2–3 days after challenge) and significantly increased IL-6 activity." (PMID 29281663, 2017). "It has been suggested that interleukin-6 produced by the tumor gives rise to pyrexia in pheochromocytoma." (PMID 27579040, 2016). "Most patients experienced chills and pyrexia while plasma cytokine profiling evidenced IL-6 and IL-8 to be significantly increased with peak concentrations at 6 to 9 hours after the start of the infusion." (PMID 27058902, 2016). "In summary, TNF appeared in the plasma before the onset of symptoms, IL-6 was detected as symptoms developed, and IL-8 was detected in plasma well after the onset of rigor and pyrexia." (PMID 24198733, 2013). "Fever and serum haptoglobin are acute-phase responses induced by a variety of cytokines, including IL-1, IL-6 and IFN-γ." (PMID 22435642, 2012). "Fever is triggered by the release of various cytokines, notably IL-1, IL-6 and TNFα which in turn can affect the immune response and defense mechanisms in a complex way." (PMID 23351502, 2012). "Under fever conditions, different kinds of endogenous anti-inflammatory cytokines are induced, both pyrogenic such as IL-1α and -β, IL-6, IL-8 and interferon-γ (IFNγ), and antipyretic, such as IL-10 and TNFα." (PMID 23166650, 2012).